TRPC4 (transient receptor potential cation channel subfamily C member 4)
Diseases named in the same sentence as TRPC4 in open-access papers (continued):
Sharing a sentence is not in itself a finding about the gene and the disease.
cancer (continued). "Interestingly, the plant derived compound Englerin A induces cytotoxicity in some cancer cell lines expressing TRPC4 and TRPC5 by enhancing channel activity; thus, increasing cytosolic Ca2+ and so Na+ concentrations." (PMID 32138386, 2020). "Anti-cancer cell effects of EA are critically-dependent on TRPC4." (PMID 30038709, 2018). "Notably, although (-)-englerin A was selectively cytotoxic to cancer cell lines, adverse reactions were observed in mice and rats after (-)-englerin A injections, which were mediated by the TRPC4/5 channels." (PMID 30463370, 2018). "Activation of an ion channel would be more consistent with the rapid (<1 h) onset of cell death induced by (−)-EA, and analysis of >500 well characterized cancer cell lines revealed that TRPC4 mRNA abundance is the feature best correlated with sensitivity to (−)-EA." (PMID 27875305, 2017). "The sesquiterpene (−)Englerin A (EA) is an organic compound from the plant Phyllanthus engleri which acts via heteromeric TRPC4/C1 channels to cause cytotoxicity in some types of cancer cell but not normal cells." (PMID 29209034, 2017). "Increased motility of cancer cells is a prerequisite for cancer invasion and metastasis, and our findings may point towards a key role for TRPC4 in progression of certain types of MB." (PMID 28627017, 2017). "(-)-Englerin A (EA), a natural product obtained from Phyllanthus engleri, can selectively activate TRPC4/5 and therefore inhibit tumor growth, suggesting activation of TRPC4/5 might be a strategy to cure certain types of cancer." (PMID 33683200, 2021). "Indeed, inhibition of Na+/K+-ATPase by ouabain increases the EA-evoked cytotoxicity, suggesting that EA-mediated cancer cell cytotoxicity sustains Na+ entry through the heteromeric TRPC1/TRPC4 channels and EA cytotoxicity can be increased by Na+/K+-ATPase inhibition." (PMID 31801263, 2019). "Importantly, the cytotoxicity of EA against cancer cells is strongly TRPC4-dependent." (PMID 30038709, 2018). "A TRPC4-specific agonist, should it be developed, might therefore be an approach for achieving an anti-cancer effect with tolerable toxicity, but careful dose-dependency studies would be needed with a stable analogue of the agonist before clinical trials could reasonably be considered." (PMID 30038709, 2018). "Further analysis of cell lines revealed that EA is a potent activator of TRPC4 and TRPC5 channels and TRPC4 expression correlates with EA sensitivity of cancer cell lines." (PMID 35165752, 2022). "Support of Ca2+ overload being a vulnerability for cancer is that TNBC cell lines with increased TRPC4 and TRPC5 showed increased sensitivity to the TRPC4 and TRPC5 activator englerin A (EA) compared to cell lines with reduced expression." (PMID 32046188, 2020). "In contrast, the potent TRPC4 and TRPC5 channel activator (-)-englerin A showed pronounced cytotoxic effects on diverse cancer cell lines, with an EC50 value of ~20 nM." (PMID 30463370, 2018). "Despite this recommendation for caution, we conclude that TRPC4 and TRPC5 represent potentially attractive targets for cancer therapeutics." (PMID 27289383, 2016). "There are still few studies of TRPC4 and TRPC5 and TRPC4- and TRPC5-containing channels in cancer cell lines and even fewer on human cancer itself." (PMID 27289383, 2016). "In this work, we identified TRPC4 and TRPC5 as the cellular efficacy targets of englerin A which lead to growth inhibition in cancer cell lines." (PMID 26098886, 2015). "Thus, in this study, we focused on TRP channels in pan-cancer and screened two typical TRP channels, TRPV4 and TRPC4, as examples." (PMID 36830651, 2023). "Gramicidin-A induced cell-death was totally resistant to Pico145, importantly suggesting that Na+ loading itself is cytotoxic for cancer cells even without activation of TRPC4/C1." (PMID 29209034, 2017). "TRPC4 is located at chromosomal locus 13q13.1-q13.2, a region that is not commonly amplified in cancer." (PMID 26098886, 2015).
cancer (continued). "At this stage, we can say that, in principle, it turns out to be possible to achieve rapid cytotoxicity through a potent and highly efficacious activator of TRPC4/TRPC5-containing channels and that such an agent might have potential as a starting point for a novel anti-cancer drug." (PMID 27289383, 2016). "TRPC4 in particular is regarded as a proton-sensitive, non-selective, receptor-operated cation channel which is important for calcium homeostasis, and its role in cancer may involve changes in the intracellular Ca2+ concentration." (PMID 36674553, 2023). "In addition, the TRPC4 and TRPC5 channels might play a pathophysiological role in cancer cells." (PMID 30463370, 2018). "Not much is known regarding the importance of TRPC4 or TRPC5 in enhancing migration and invasion of cancer cells, although at least TRPC4 seems to have a role in proliferation and tumor formation." (PMID 32138386, 2020). "Because the most common cancer cell cytotoxic effect of EA requires TRPC4 and not TRPC5, the study suggests partial overlap of the potential anti-cancer effect and the adverse reaction of EA." (PMID 30038709, 2018).
tumor (22 papers, 2010 to 2025). "Studies on cBioportal were analyzed for mutation frequencies of TRPC4 in the investigated tumor entities." (PMID 36674553, 2023). "Moreover, we analyzed the correlation of two members of the TRP family, namely TRPV4 and TRPC4, with tumor mutational burden (TMB) and microsatellite instability (MSI), as well as the genes related with immune activation." (PMID 36830651, 2023). "A substance called englerin A, isolated from the African plant phyllanthus engleri, can activate the ion channels TRPC4 and TRPC5 at nanomolar concentrations and it can inhibit the growth of tumor cell lines expressing high levels of TRPC4 or TRPC5." (PMID 36674553, 2023). "On the contrary, TRPC4 is markedly downregulated in renal cell carcinoma cell lines and is correlated with tumour angiogenesis." (PMID 32575381, 2020). "Furthermore, it limits the proliferation of tumor cell lines with an increased TRPC4/TRPC5 presence." (PMID 40723382, 2025). "As solid tumors exhibit an inversed pH-gradient with lowered extracellular and increased intracellular pH, both contributing to tumor progression, TRPC4 might be a signaling molecule in the altered tumor microenvironment." (PMID 36674553, 2023). "However, the effect of the TRPC4/5-NHERF protein complex on tumor growth has largely remained elusive until now." (PMID 30463370, 2018). "In contrast, our previous studies have suggested that EA is a potent and selective activator of canonical transient receptor potential channel 4 (TRPC4) and 5 (TRPC5), and we have proposed that EA causes anti-tumor cell activity by Na+ loading into cells through heteromeric TRPC4/C1 channels." (PMID 29209034, 2017). "Two other groups have reported that englerin A inhibits tumor cell growth by activating the transient receptor potential cation channel, subfamily C, member 4 (TRPC4) ion channel, while a third group reported that englerin A antagonized L-type calcium channels." (PMID 28296891, 2017). "The data suggested the hypothesis that englerin A inhibits tumor cell line growth by activating the transient receptor potential cation channel, subfamily C, member 4 (TRPC4) ion channel." (PMID 26098886, 2015). "These experiments confirm that activation of TRPC4/C5 channels inhibits tumor cell line proliferation and confirms the TRPC4 target hypothesis generated by the cell line profiling." (PMID 26098886, 2015). "It is possible that increased levels of TRPC4 may potentiate a GPCR pathway that confers a proliferation or survival advantage to the tumor cell lines." (PMID 26098886, 2015). "We screened eight different types of tumor and non-tumor cells derived from human tissues by evaluating the TRPC4 mRNA gene expression with quantitative PCR and measuring the functional expression of Ca2+-permeable TRPC4 and/or TRPC5 with Ca2+-response to 30 nM EA." (PMID 29209034, 2017). "Considering the results of the differential expression of TRP family genes between tumor and para-carcinoma tissues and RNAss, DNAss, and TME scores, we selected TRPC4 and TRPV4 as the representative TRP family genes." (PMID 36830651, 2023). "High expression of TRPM4 and TRPM7 was detected in primary tumor biopsies, while TRPV4, TRPC4, TRPC6 and especially TRPV6 expression was limited, while the expression of TRPC1 and TRPV2 are moderately expressed." (PMID 34936030, 2021). "In conclusion, our results reveal that EA exhibits anti-tumor cell activity in SW982 cells and that heteromeric TRPC4/C1 channels in these cells are a critical target of EA." (PMID 29209034, 2017). "In conclusion, englerin can activate TRPC4 and TRPC5 ion channels at nanomolar concentrations, and englerin A can inhibit growth of tumor cell lines which express high levels of TRPC4 or TRPC5." (PMID 26098886, 2015). "The mechanism(s) by which TRPC4 channel agonism leads to growth inhibition in tumor cell lines are not obvious." (PMID 26098886, 2015).
tumor (continued). "The absence of TRPC4 in renal cell carcinoma results in impaired Ca2+ intake, misfolding, retrograde transport, and diminished antiangiogenic thrombopsonin-1 production, thus enabling angiogenic switch during tumor progression." (PMID 36588677, 2022). "It is also not clear why some tumor cell lines express TRPC4 at high levels." (PMID 26098886, 2015).
infection (2 papers, 2019 to 2024). The state of being infected such as from the introduction of a foreign agent such as serum, vaccine, antigenic substance or organism. "At 72 h post infection (hpi), TRPC4 protein levels in the ZIKV-infected cells were assessed by using immunofluorescence staining and western blots." (PMID 39009885, 2024). "We first noticed that host TRPC4 protein levels were increased by ZIKV (SMGC-1 strain) infection in BHK (Baby Hamster Syrian Kidney) cell monolayers which were inoculated with ZIKV at a multiplicity of infection (MOI) of 0.001 or 0.01." (PMID 39009885, 2024). "We subsequently compared the RNA expression levels of TRPC4 and ZIKV in BHK cells at 48 h and 72 h post infection." (PMID 39009885, 2024).
neurological disorder (2 papers, 2023). "Previous studies have revealed the critical involvement of TRPC4 and TRPC5 in a host of neurological disorders." (PMID 37765099, 2023).
psychiatric disorder (2 papers, 2015 to 2018). A disorder characterized by behavioral and/or psychological abnormalities, often accompanied by physical symptoms. "Taken together, the data presented provide a strong rationale for considering TRPC4 and TRPC5 as targets for the alleviation of symptoms associated with human psychiatric disorders." (PMID 29385160, 2018). "However, to what extent the TRPC4/C5 channels are involved in psychiatric disorders remains unexplored." (PMID 26317356, 2015).
bacterial infections (1 paper, 2018). "Further in vitro and in vivo studies addressing the potential of TRPC4/TRPC5 selective agonists as protective molecules against bacterial infections remain to be investigated." (PMID 29983857, 2018).
gastrointestinal disorders (1 paper, 2020). "Direct TRPC4 agonists may be used for the correction of gastrointestinal disorders provoked by general anesthesia." (PMID 33390980, 2020).
renal diseases (1 paper, 2024). "The inhibitors of TRPC4/5 have the potential for the treatment of CNS diseases and renal diseases." (PMID 39611176, 2024).
TRPC4 also shares sentences with these, for which no sentence is quoted: breast carcinoma (3 papers); Hypertension (3); cardiovascular disease (2); schizophrenia (2); squamous cell carcinoma (2); adenocarcinoma (1); anxiety disorder (1); Arthritis (1); basal cell carcinoma (1); Bladder (1); central nervous system disorder (1); cervical cancer (1); cervical squamous cell carcinoma (1); channelopathies (1); clear cell renal cell carcinoma (1); dry eye (1); dyslipidaemia (1); Erythema (1); focal cortical dysplasia type II (1); Gillespie syndrome (1); heart failure (1); hyperglycaemia (1); Hypothermia (1); Intellectual disability (1); internalizing disorder (1); kidney damage (1); Obesity (1); progressive ataxia (1); skin inflammation (1); tuberous sclerosis complexes (1).
A further 2 diseases each share a sentence with TRPC4 in 1 paper.